CPT2 (carnitine palmitoyltransferase 2)
Diseases named in the same sentence as CPT2 in open-access papers (continued):
Sharing a sentence is not in itself a finding about the gene and the disease.
schizophrenia (1 paper, 2024). A major psychotic disorder characterized by abnormalities in the perception or expression of reality. "This study also presents novel findings linking CPT2 deficiency to the regulation of schizophrenia and neurodegenerative disease-associated genes." (PMID 39199302, 2024). "RT-qPCR analyses showed significant increases in the expression of schizophrenia-associated genes in CPT2 knockdown compared to control zebrafish." (PMID 39199302, 2024). "Our previous work documented a case study of CPT2 deficiency comorbid with early childhood seizures and the development of schizophrenia later in life." (PMID 39199302, 2024). "Our work described a proband with confirmed CPT2 deficiency who presented with mild-to-moderate symptoms that included seizure during early childhood, neurocognitive deficits in adolescence, and schizophrenia as a young adult." (PMID 39199302, 2024). "Previously, we reported that human CPT2 deficiency in a male proband was comorbid with seizures in early development and schizophrenia in early adulthood." (PMID 39199302, 2024). "CPT2 deficiency is a genetic disorder that we recently showed can be associated with schizophrenia." (PMID 39199302, 2024). "CPT2 mutation may underlie our proband’s epilepsy, neurocognitive challenges, and later-presenting schizophrenia." (PMID 39199302, 2024). "We hypothesize that CPT2 deficiency during early brain development causes transcriptional, structural, and functional abnormalities that may contribute to a CNS environment that is susceptible to the emergence of schizophrenia." (PMID 39199302, 2024). "The goal of this study was to develop an accessible vertebrate model system, which is highly homologous to humans, to begin to investigate the effects of CPT2 deficiency on early neurodevelopmental events that may help explain the putative association to schizophrenia susceptibility." (PMID 39199302, 2024). "CPT2 knockdown zebrafish were evaluated for changes in gene expression related to mitochondrial function, neurotransmitter function and signaling, and schizophrenia-like disease states at the early larvae stage." (PMID 39199302, 2024). "Interestingly, genes considered to be markers for schizophrenia and other synucleinopathies were upregulated in CPT2 knockdown zebrafish larvae." (PMID 39199302, 2024). "CPT2 deficiencies in humans result in a variety of clinical outcomes depending on the severity of the CPT2 mutation; however, mild-to-moderate CPT2 deficiency had not previously been linked to the development of schizophrenia." (PMID 39199302, 2024). "While CPT1 deficiency is associated with neurocognitive deficits, CPT2 deficiency had not been associated with neurocognitive deficits and schizophrenia." (PMID 39199302, 2024).
tumor (52 papers, 2013 to 2026). "Leptin secreted from adipocytes activates JAK-STAT3 signaling pathway in breast cancer stem cells (BCSCs), which heightens FAO via STAT3 association with CPT2 promoter, contributing to tumor spheroid forming." (PMID 40290117, 2025). "Our findings indicated that forced expression of CPT2 significantly rescued the suppression of cell proliferation and invasion in vitro, as well as tumor growth and metastasis in vivo, which were caused by SLC44A2 overexpression." (PMID 40592838, 2025). "The high expression of CPT2 in GBM has been associated with free fatty acids promoting tumor development." (PMID 39491527, 2024). "We preliminarily recognize CPT2 as a potential tumor-suppressor gene and is associated with a state of neutrophil infiltration." (PMID 36177002, 2022). "Among the prognostic risk model genes, TYRO3 and CPT2 demonstrated strong tumor-suppressive potential, aligning with mRNA-level analyses in which both genes showed negative correlation coefficients within the risk model—further supporting their protective roles in KIRC." (PMID 40969770, 2025). "Moreover, we found that the expressions of SLC25A42 and CPT2 were positively associated in tumor tissues from GC patients." (PMID 40246810, 2025). "Besides, CPT2 levels in tumor tissue were found to be associated with oxaliplatin-based chemotherapy sensitivity." (PMID 34740325, 2021). "Downregulations and tumor suppressive functions of CPT2 have been observed in ovarian, liver and renal cancers." (PMID 40592838, 2025). "We also examined the association between CPT2 and SLC44A2 in tumor tissues from CRC patients using IHC staining-based histological analysis and found a notable inverse correlation between CPT2 and SLC44A2 protein levels." (PMID 40592838, 2025). "IF and IHC staining showed that lower GSTK1 expression in tumor tissues had higher expression of p-DRP1 (Ser616) or lower CPT2, CACT, and BBOX." (PMID 41276823, 2025). "Consistent with this, IHC staining of CPT2 in tumor tissues from nude mice showed significantly lower CPT2 levels in the SLC44A2 overexpression group compared to the control group." (PMID 40592838, 2025). "In summary, our study provides a molecular basis for SLC44A2 as a potential tumor suppressor in CRC by downregulating CPT2-mediated mitochondrial FAO in a MUL1-dependent manner (Graphical abstract, generated using the Microsoft PowerPoint software)." (PMID 40592838, 2025). "The results showed that lncBCL2L11 was negatively correlated with CPT2 and lncBCL2L11 levels were significantly higher in tumor tissues than in paracancerous tissues." (PMID 38519939, 2024). "Knockdown experiments reinforced that diminished ACOX1 and CPT2 expression contribute to malignancy, influencing proliferation, apoptosis evasion, and tumor invasiveness." (PMID 38594466, 2024). "Materials and methods: By mining the TCGA database, we screened out carnitine palmitoyltransferase-2 (CPT2), a key enzyme in the fatty acid β-oxidation (FAO) process associated with anti-tumor immunity." (PMID 37251324, 2023). "In particular, we found that carnitine and short-chain acylcarnitines were reduced in concentration in HB and that the carnitine metabolic pathway was dysregulated in the tumours (CPT1a, CPT2 and SLC25A20)." (PMID 37958356, 2023). "Subsequently, we next used the TIMER website to examine the differential expression of CPT2 in various tumor tissues and normal tissues." (PMID 37251324, 2023). "CPT2 influences tumor development in various cancer, and its low expression correlates with poor prognosis and a worse overall survival rate in patients with CRC." (PMID 36465397, 2022).
tumor (continued). "It was noticed from the results of the study that in tumor cell lines, both the protein and mRNA levels of CPT2 was significantly down-regulated, which was the same as the results of the public database." (PMID 36195841, 2022). "In the UALCAN database, it was observed that CPT2 was down-regulated in CRC tissues and the expressions of CPT2 were significantly negatively associated with tumor stage." (PMID 36195841, 2022). "In summary, CPT2 can provide new insights about the progression and occurrence of the tumor as it acts as an independent prognostic factor in CRC sufferers." (PMID 36195841, 2022). "The expression levels of CD36, PTGR1, SUCLG2 and CPT2 were significantly decreased in tumor tissues." (PMID 36568396, 2022). "The expression of CPT2 in COAD and READ was further explored through the GEPIA website and the results showed that by comparing with normal tissues, the level of CPT2 expression was extremely low in tumor tissues." (PMID 36195841, 2022). "Next, we collected CRC tissues (n = 24) and adjacent non-tumor tissues (n = 8) and analyzed mRNA levels by qRT-PCR, and proteins levels of CPT2 in CRC cell lines by western blotting." (PMID 36195841, 2022). "This suggests that CPT2 was upregulated in the tumour invasive margin, where miR-619-5p is downregulated, relative to the tumour core/rim, where miR-619-5p miRNAs is upregulated." (PMID 34354095, 2021). "When conducting immunohistochemical staining of GBM tissue microarrays (TMAs), we found that CPT2 expression was higher in the invasive edge relative to the tumour core and rim regions." (PMID 34354095, 2021). "Our results regarding CPT2 expression, which follows a similar pattern to CACT, are also consistent with previous findings showing that CPT2 is downregulated in HCC and is associated with tumor differentiation grade and vascular invasion." (PMID 34679988, 2021). "Subsequently, in each tumour region, we calculated the percentage of cells containing CPT2-positive cytoplasmic staining per field of view to determine statistical significance." (PMID 34354095, 2021). "Here, we used immunohistochemistry to examine the expression of the remaining three components of CS (CACT, CPT2, and CrAT) in a series of 32 spontaneous CMTs and compared their expression with the degree of tumor malignancy." (PMID 34679988, 2021). "As the tumor stage advanced, the CPT2 expression level decreased accordingly, revealing a negative correlation." (PMID 32953885, 2020). "The violin plot based on TCGA data displayed remarkably different expression levels of ALDH3A2, B3GAT3, and CPT2 in tumor group compared with that of the normal group." (PMID 33194661, 2020). "Our results indicate that SLC44A2 acts as a tumor suppressor in CRC by downregulating CPT2-mediated mitochondrial fatty acid oxidation via increasing the interaction between MUL1 and CPT2, supporting SLC44A2 as a potential therapeutic target in the treatment of this malignancy." (PMID 40592838, 2025). "We next analyzed the correlation between lncBCL2L11 and CPT2 in paired tumor tissues." (PMID 38519939, 2024). "In addition, upregulation of CPT2 has been shown to attenuate CRC tumor development and increase chemosensitivity via a hyperactive Wnt/β-catenin pathway in vivo." (PMID 37251324, 2023). "Furthermore, it is identified that CPT2 was overexpressed in normal tissues compared with tumor tissues by TNMplot analysis." (PMID 37251324, 2023). "We have also demonstrated that increased CPT2 gene expression could enhance the level of tumor immune cell infiltration." (PMID 37251324, 2023). "However, CPT2 was shown to be downregulated in HCC tissues and associated with vascular invasion and tumor tissue differentiation." (PMID 37251324, 2023). "Results indicated that CPT2 was strongly marked in normal tissues than tumor tissues." (PMID 37251324, 2023).
tumor (continued). "Similarly, down-regulation of CPT2 also inhibited fatty acid β-oxidation in the tumor microenvironment and promoted cancer progression through acylcarnitine accumulation." (PMID 36568252, 2022). "We also found the expression of CPT2 decreased in tumor stage III-IV compared to stage I-II." (PMID 36195841, 2022). "We primarily reveal that CPT2 was related to tumor immune infiltration and may act as a valuable biomarker for COAD immunotherapy." (PMID 36177002, 2022). "Moreover, this study revealed that down-regulation of CPT2 expression promotes tumor cell proliferation and provides a new potential target for improving the therapeutic effect of drugs against CRC." (PMID 36195841, 2022). "Since the expression of both miR-619-5p and miR-4793-3p were found to be upregulated in the tumour core and rim relative to the invasive margin region, the expression of their putative target, CPT2, was expected to be downregulated in the tumour core and rim relative to the invasive margin." (PMID 34354095, 2021). "In addition, IHC staining of tumor sections showed that CPT2 knockdown markedly reduced proliferation as indicated by Ki‐67 staining." (PMID 33207079, 2021). "In addition, a set of enzymes responsible for carnitine shuttling, which are encoded by SLC22A1, SLC25A20, SLC25A29, and CPT2, are downregulated in HCC tumor cells." (PMID 33424926, 2020). "Unfortunately, the role of CPT2 in tumor immune microenvironment remains unknown." (PMID 37251324, 2023). "Hence, our study revealed that CPT2, a key enzyme in the FAO process, was positively associated with the level of immune cell infiltration, which suggested that CPT2 could affect tumor progression by reprogramming lipid metabolism in the TIME." (PMID 37251324, 2023). "Moreover, CPT2 protein expression correlated with the decrease in tumor differentiation." (PMID 34679988, 2021). "Moreover, CPT1C may be a key element of mitochondrial dysfunction-associated tumor cellular proliferation and senescence and functionally differs from the other three subtypes CPT1A, CPT1B and CPT2 11,12." (PMID 32641987, 2020). "Functionally, MAFF-mediated repression of CPT2 diminishes fatty acid oxidation and enhances tumor invasion, underscoring a dual role whereby MAFF drives tumor progression yet primes cells for ferroptotic death." (PMID 42209456, 2026). "Similar to CPT2, MUL1 acts as an oncogene and as a tumor suppressor in different cancer types depending on the different targets." (PMID 40592838, 2025). "Tumor cells transfected with si-ACOX1 and si-CPT2 also exhibited enhanced migration and invasion in transwell assays." (PMID 38594466, 2024). "According to the analysis of the TCGA data, the expression of MIPEP and NFS1 was higher in tumor tissues in comparison with that in normal tissues; however, the expression of CPT2 and ISCU was lower in tumor tissues in relative to that in normal tissues." (PMID 36776001, 2023). "CPT2, a key molecule in lipid metabolism, and the crosstalk between tumor metabolites including Malonyl-CoA, 1,1-Dimethylbiguanide, L-Palmitoylcarnitine, Estradiol, Propionyl-CoA, Palmityl-CoA, Palmitaldehyde, Coenzyme A, and Palmitic acid may offer new hope for tumor immunotherapy." (PMID 37251324, 2023). "The expression levels of CDKN2A were upregulated whereas GAP43, CPT2 and NRG1 were downregulated in tumor tissues of CRC patients." (PMID 37205121, 2023). "Clinical samples showed significant downregulation of the following genes: CPT2, ACAA2, HPGD and ALDH3A2, while the expression of ENO2, TDO2, CPOX, ACADL and PTPRG was significantly upregulated in the tumor tissue (p < 0.01)." (PMID 36230866, 2022). "Here we show that MUL1-mediated downregulation of CPT2 play a crucial suppressive role in CRC progression, suggesting that MUL1 may function as a potential tumor suppressor in CRC, which still needs more investigations." (PMID 40592838, 2025).
tumor (continued). "There was no significant change found in tumour tissue compared to non-tumour tissue with regard to CPT2 expression." (PMID 37958356, 2023). "Conversely, the expression of protective types (ACOX1, CPT2, ELOVL6, SUCLG2) was reduced in the H-R cohort than in the L-R cohort, implying that the eight-gene model accurately predicted prognosis and their possible effect on tumor incidence and growth." (PMID 38186579, 2023). "The expression of CD36, PTGR1, SUCLG2, CPT2 and ELOVL6 were downregulated in tumor tissues." (PMID 36568396, 2022). "As such, we could not make assertions regarding CPT2 protein expression in the infiltrating tumour cells in the invasive margin region compared to the tumour cells in the core/rim regions." (PMID 34354095, 2021). "The largest number of changes in gene expression (n = 8) between tumour and non-malignant groups were identified in metabolic genes (PFKL, ATP5A1, UQCRFS1, CPT2, COX5A, ACLY, GPD2, and G6PD)." (PMID 36142793, 2022).
cancer (27 papers, 2017 to 2026). A tumor composed of atypical neoplastic, often pleomorphic cells that invade other tissues. "Despite the aberrant expression of CPT2 in multiple cancer types, the underlying molecular mechanisms, especially from mitochondrial, leading to the aberrant expression of CPT2 remain largely unclear." (PMID 40592838, 2025). "Numerous findings have emphasized that CPT2 is closely associated with malignant biological processes in a wide range of cancers." (PMID 39596847, 2024). "We found that CPT2 was highly expressed in most normal tissues compared to cancers, and its low expression was associated with poor prognosis in LGG." (PMID 37251324, 2023). "The mutation type, frequency, CAN, and structural variant of CPT2 in all TCGA cancers were obtained from the cBioPortal website." (PMID 37251324, 2023). "CPT2 expression was also associated with the prognosis of human cancers, suggesting that CPT2 may be a potential biomarker for predicting the efficacy of cancer immunotherapy." (PMID 37251324, 2023). "Carnitine palmitoyltransferase 2 (CPT2), a rate-limiting enzyme in FAO, has been implicated in various diseases, including cancer." (PMID 40592838, 2025). "In the current study, we investigated the impact of CPT2 on pan cancer and the resulting clinical implications." (PMID 37251324, 2023). "In this study, we explored the expression of CPT2 in human cancer and identified its relationship with the level of immune cell infiltration." (PMID 37251324, 2023). "It is interesting to note that while CPT1A and CPT2 are involved in the same metabolic pathway, their levels of expression, such as CPT1A upregulation and CPT2 downregulation, can have opposite effects in different types of cancer." (PMID 37601653, 2023). "To better understand the role of CPT2 in cancer development and prognosis, we performed comparative data mining on numerous gene expression data sets." (PMID 37251324, 2023). "Mechanistically, nuclear factor of activated T cells 3 (NFATc3) promoted CPT2 expression transcriptionally, and inhibiting CPT2 resensitized cancer cells to oxaliplatin." (PMID 35646898, 2022). "In G2- and G3-carcinomas, CPT2 protein expression was restricted to regions where mammary gland morphology was still preserved." (PMID 34679988, 2021). "CPT2 immunoreactivity was weak in NMGs and increased in 72% of G1 carcinomas, with strong and diffuse cytoplasmic CPT2 immunostaining." (PMID 34679988, 2021). "In contrast, in patients with gastrointestinal cancers that were poorly treated with oxaliplatin, the combination of perhexiline, an inhibitor of CPT2, and oxaliplatin was able to significantly reduce cancer cell survivability from chemotherapy via the ROS/NFATc3/CPT2 axis." (PMID 39596847, 2024). "Analysis of CPT2 in pan-cancer illustrated that CPT2 is amplified in a subset." (PMID 37251324, 2023). "Nevertheless, the impact of CPT2 on the progress of cancers is still not well understood." (PMID 37251324, 2023). "Subsequently, the relationship between CPT2 and survival was analyzed in cancer patients." (PMID 37251324, 2023). "Compared to CPT1 isoforms, less is known about CPT2 deregulation in cancer; nevertheless, a recent study has reported that this enzyme could be considered as an independent prognostic factor in colorectal cancer patients." (PMID 29445084, 2018). "Our results show that cancer tissues down-regulate the expression of CPT2 and that higher expression of CPT2 in cancer tissue independently predicts better prognosis in CRC patients, indicating the important role of fatty acid oxidation, especially CPT2, in cancer progression." (PMID 28977850, 2017). "Second, although we observed the prognostic value of CPT2 in CRC patients, the molecular mechanism by which CPT2 affects cancer progression is unknown." (PMID 28977850, 2017).